STAT3 (signal transducer and activator of transcription 3)
Diseases named in the same sentence as STAT3 in open-access papers (continued):
Sharing a sentence is not in itself a finding about the gene and the disease.
multiple myeloma (continued). "As IL-21 is also anti-apoptotic for myeloma cells, it is tempting to speculate that IL-21 could contribute to STAT3 activation in vivo in the setting of this malignancy." (PMID 24600453, 2014). "In addition, inhibition of Hsp90 using pharmacological inhibitors (17-DMAG) or siRNA decreased levels of pStat3 in human primary hepatocytes and levels of total Stat3 in multiple myeloma cells." (PMID 24756126, 2014). "Furthermore, inhibition of STAT3 has been shown to sensitize the U266 myeloma cell line to apoptosis induced through conventional chemotherapy agents." (PMID 24803933, 2014). "STAT3 besides self-renewal might also prevent apoptosis in a proB-cell line and in T cells, and constitutive activation of STAT3 blocks apoptotic processes in myeloma cells." (PMID 23880850, 2013). "AG490 also inhibits STAT3 signaling in multiple myeloma and Hodgkins lymphoma." (PMID 24199193, 2013). "It has been found that upregulation of the gene encoding the oncogenic miR-21 is also STAT3 dependent and overexpression can promote survival of myeloma cells in the absence of IL-6." (PMID 24416592, 2013). "Next, we investigated whether STAT3 signaling is involved in the synergistic regulation of multiple myeloma cell survival by the cotreatment of decursin and doxorubicin." (PMID 23818927, 2013). "Similarly, GRK6 silencing in myeloma cells induced a tumor suppressor effect by inhibiting STAT3 phosphorylation and decreasing tumor cell survival." (PMID 23497290, 2013). "The TrkB signaling pathway overlaps with the ERK/MAPK or JAK2/STAT3 signaling pathway in myeloma or endometrial cancer cells, which prompted us to examine whether TrkB suppressed miR-204-5p expression via these signaling pathways." (PMID 24321270, 2013). "Phosphorylation of STAT3 has been shown to be impaired in myeloma cells after incubation with MPA." (PMID 22571761, 2012). "Stat3 (Signal transducer and activator of transcription 3) is an oncogene activated in many cancers including breast, prostate, lung, head and neck and colon, liver, pancreas, and multiple myeloma." (PMID 22879872, 2012). "In this study, we reported a novel interaction between 14-3-3ζ and Stat3 in myeloma cells." (PMID 22279540, 2012). "We also found that genipin and icariside II could be applied for multiple myeloma therapy by inducing apoptosis and targeting the signaling molecules such as STAT3." (PMID 22260501, 2012). "Consistent with the evidences by Pandey and colleagues that BA suppressed STAT3 activation in multiple myeloma cells, BA prevented hypoxia-induced tyrosine phosphorylation, DNA binding activity and nuclear translocalization of STAT3, suggesting the inhibitory effect of BA on STAT3 activation." (PMID 21731766, 2011). "Thus, our findings clarify the SKP2/ p27Kip1-independent mechanisms of CKS1B activity in maintaining myeloma cell growth and survival, and also provide a rationale for specifically targeting STAT3 and MEK/ERK/BCL2 in aggressive CKS1B-overexpressing MM." (PMID 20930946, 2010). "Thus, it is reasonable to conclude that CKS1B mediates myeloma cell growth and drug-resistance through activation of STAT3 and MEK/ERK/BCL2 signaling pathways." (PMID 20930946, 2010). "In multiple myeloma, for example, the inhibition of IL-6 receptor signaling through STAT3 was shown to induce apoptosis, an indication that IL-6-mediated STAT3 activation contributes to the pathogenesis of multiple myeloma by increasing the survival potential of tumor cells." (PMID 17324269, 2007). "Interleukin-6 is produced by MM cells and promotes myeloma cell proliferation in an autocrine manner through phosphorylation of the signalling protein STAT3." (PMID 15970928, 2005). "Notably, IL-6 upregulates Mcl-1 expression through the JAK/STAT3 signaling pathway, which not only induces the proliferation and survival of multiple myeloma cells but also increases mitochondrial bioenergy production and confers protection against mitochondrial dysfunction in cortical neurons." (PMID 39272918, 2024).
multiple myeloma (continued). "Importantly, the oncogenic effects of STAT3 have been well established, and constitutive activation of the STAT3 signaling pathway is essential for survival in several tumor-derived cell lines, including those derived from multiple myeloma, astrocytoma, in addition to head and neck cancers." (PMID 38339245, 2024). "In addition, the oncoprotein BCR-ABL (Breakpoint-cluster region and Abelson leukemia proteins) derived from nRTKs mutation (chromosomal rearrangement) are associated with the development of hematological malignancies, either leukemia, lymphoma, or myeloma via STAT3 signaling." (PMID 38245798, 2024). "Thus, a class switch strategy targeting the c-MYC gene and STAT3 activation via IL-6 with PI-containing therapy may be a reasonable option for LEN-refractory myeloma." (PMID 38004369, 2023). "Signal transducer and activator of transcription 3 (STAT3) activation via IL-6 autocrine is associated with LEN-resistance, and bromodomain for CRBN binding protein/E1A binding protein p300 (CBP/EP300) inhibition can release LEN-refractoriness via the STAT3-activated myeloma cell line." (PMID 38004369, 2023). "However, CAMKIIγ knockdown reduced the levels of p-ERK and STAT3 in multiple myeloma cells." (PMID 35269900, 2022). "In previous reports, activation of STAT3 was detected in a wide variety of human cancer cells, including head and neck, brain, breast, gastric, colorectal, liver, lung, kidney, pancreas, prostate, ovarian, cervical cancer, multiple myeloma, and acute myeloid leukemia." (PMID 34679602, 2021). "Moreover, we found that 3D-cultured myeloma cell lines underwent apoptosis after STAT3 inhibition." (PMID 34201211, 2021). "Importantly, the JAK1/STAT3 pathway was previously shown to alter proteasome inhibitor sensitivity in multiple myeloma, and therefore could possibly induce bortezomib resistance in the case of TKI-resistant CML." (PMID 33712704, 2021). "Overall, bavachin targets STAT3 and could be used for the treatment of multiple myeloma." (PMID 32545187, 2020). "Notably, STAT3 activation is associated with the severity of wasting in both the C‐26 and Apcmin/+ models of cancer cachexia, and AR‐42 was previously shown to suppress the IL‐6/GP130/STAT3 signaling axis in multiple myeloma cells." (PMID 31930715, 2020). "However, there might be other mechanisms, by which STAT3 and STAiR18 promote myeloma cell survival and which remain to be elucidated." (PMID 32041604, 2020). "Interestingly, previous studies also demonstrated that STAT3 S-nitrosylation suppressed microglia proliferation, multiple myeloma cell survival and proliferation microglia proliferation, multiple myeloma cell proliferation and abnormal proliferation by inhibiting STAT3 phosphorylation." (PMID 31801946, 2019). "Moreover, inhibition of NF-κB pathway by bortezomib is considered to be as one of major factors for its anti-myeloma activity, although several other oncogenic signal transduction cascades such as STAT3/Akt and ERK kinase have also been reported to be modulated upon bortezomib treatment." (PMID 29773987, 2018). "Thus, Reelin-induced phosphorylation of Akt and STAT3 may act in concerto to promote myeloma cell growth." (PMID 28345605, 2017). "Thus, piperlongumine may exert anti-myeloma effects by specifically inhibiting Cys712-dependent STAT3 activation." (PMID 27634873, 2016). "Therefore, we may postulate that icaritin can exert anti-myeloma effects in vivo via suppressing “p-JAK2/p-STAT3/VEGF”-mediated signaling pathway." (PMID 25865044, 2015). "Also, our group reported that decursin has a protective effect on neurotoxicity and nephrotoxicity in normal cells via activation of antioxidative enzymes and also decursin-induced apoptosis through inhibition of STAT3 signaling pathway in multiple myeloma U266 cells." (PMID 23818927, 2013).
multiple myeloma (continued). "Moreover, a significant reduction of phospho-JAK2 and Src, the upstream tyrosine kinases of STAT3, was observed in Icariside II-treated U937 cells in a dose- and time-dependent manner, which was similarly supported by our previous report in multiple myeloma cells." (PMID 22493659, 2012). "Furthermore, BMP-2 has been shown to induce activation of STAT3 in myeloma cells." (PMID 15877825, 2005). "Promising results have been obtained in vitro for multiple myeloma, where RES inhibited the NF-κB, AKT, and STAT3 pathways and exhibited cytotoxicity against myeloma cells." (PMID 40077707, 2025). "In multiple myeloma, LILRB4 activates the STAT3‐PFKFB1 pathway to promote cancer cell proliferation." (PMID 40576161, 2025). "A study demonstrated that crocin can mediate the suppression of STAT3 and inhibit the upstream kinases JAK1, JAK2, and SRC, thereby preventing the progression of multiple myeloma." (PMID 40841966, 2025). "It is 7–12 times more effective at suppressing multiple myeloma cell growth and 6–15 times more potent at inhibiting the NF‐κB, PI3K/AKT, JAK/STAT3, and IRF4 pathways than curcumin." (PMID 39945243, 2025). "IL-21 was originally demonstrated to be a growth and survival factor in human myeloma cell lines, which was mediated through the activation of JAK1/STAT3 signaling." (PMID 38720319, 2024). "IL-21 was originally demonstrated to be a growth and survival factor in human myeloma cell lines, which is mediated through the activation of the JAK1/STAT3 signaling." (PMID 38720319, 2024). "A promising example is AZD1480, which blocks cell proliferation at low micromolar concentrations and induces apoptosis in myeloma cell lines via concomitant inhibition of the phosphorylation of signaling proteins JAK2, STAT3, and MAPK." (PMID 37373437, 2023). "Pretreatment of myeloma cells with STAT3 inhibitor, JSI-124 and bortezomib can reverse compromised DC function, generating potent myeloma-specific cytotoxic T lymphocytes (CTLs) via the inhibition of HSP90 and STAT3 activity." (PMID 35326392, 2022). "Ruxolitinib upregulates CD38 expression via inhibition of STAT3 phosphorylation, thus enhances the DARA-mediated antibody-dependent cellular cytotoxicity (ADCC) against MM cell lines and primary CD138+ myeloma cells derived from MM patients." (PMID 35326392, 2022). "Similarly, baicalein not only inhibited myeloma cell proliferation and induced apoptosis through downregulating IL-6, but also abrogated IL-6-mediated signaling cascades including JAK, STAT3, MAPK, and Akt pathways associated with the proliferation and survival of MM cells." (PMID 35153791, 2022). "It is reported that BMSCs-derived EVs suppress immune function in multiple myeloma by activating MDSCs through the STAT3/STAT1 signaling pathway, thereby promoting the development of multiple myeloma." (PMID 36439438, 2022). "Abnormal elevated STAT3 activity has been found in a variety of hematological and solid malignancies such as acute myeloid leukemia (AML), multiple myeloma, and cancers of the bladder, head and neck, kidney, pancreas, uterus, ovary, esophagus, and breast." (PMID 36061181, 2022). "For example, in myeloma cells, BMP4 inhibits DNA synthesis depending on interleukin-6 by downregulating tyrosine phosphorylation of Stat3 induced by interleukin-6 and then inhibits tumor cell proliferation." (PMID 35401213, 2022). "Many new drugs recently have been discovered through targeting the STAT3 signaling pathway, such as AZD9150, OPB-31121, and Bosutinib, and they also showed significant inhibition efficiency of many cancers, including multiple myeloma." (PMID 34923957, 2021). "In previous studies we observed in Multiple Myeloma a positive feedback between LINC00152 and the transcription factor STAT3 at the transcriptional level." (PMID 34531451, 2021). "Nitrosylation appears to be detrimental for STAT3-dependent oncogenic function in PDAC and also in multiple myeloma (MM), where SNO-STAT3 shows decreased activity." (PMID 34947954, 2021).
multiple myeloma (continued). "Knockdown of integrin α6 in myeloma cells nearly diminished the activation effect from myeloma cells on the phosphorylation of ERK1/2, STAT1, and Akt in MSCs, except STAT3." (PMID 34150666, 2021). "CKS1B was previously reported to promote drug resistance in myeloma cells through activation of the JAK/STAT3 signaling pathway, which revealed a link between CKS1B and JAK/STAT3 pathway." (PMID 34408811, 2021). "PRL-3 protein promotes STAT3 phosphorylation by deactivating SHP-2, thereby framing a feedforward loop in multiple myeloma." (PMID 35053027, 2021). "A Scutellaria radix component, Baicalein, suppressed myeloma cell survival and proliferation by blocking IκB-α degradation, followed by downregulating IL-6/JAK/STAT3 and XIAP gene levels." (PMID 34680295, 2021). "One of the best characterized pathways in this regard is the downregulation of the JAK2/STAT3 signaling pathway by increased SOCS3 expression, as described in multiple myeloma." (PMID 34204116, 2021). "Ultimately, myeloma cell biology is altered by key transcription regulators such as extracellular signal-regulated kinases (ERK1/2), signal transducer and activator of transcription 3 (STAT3), and nuclear factor-κappa B (NF-κB)." (PMID 33105696, 2020). "Curcumin was shown to block STAT3 and/or STAT5 phosphorylation in leukemia, lymphoma, and myeloma cells." (PMID 31963765, 2020). "Additionally, betulinic acid could downregulate STAT3 activation through SHP-1 in myeloma cells." (PMID 32486001, 2020). "An earlier study reported that EP can potentially induce the antitumor effects in multiple myeloma U266 cells; simultaneously, it can act as an antiangiogenic agent through the targeting of the JAK2/STAT3 signaling pathway." (PMID 30781890, 2019). "Compound 69 showed inhibition of STAT-3 and STAT-3-dependent U266 multiple myeloma cells, with IC50 values of 0.61 and 6.7 μM, respectively." (PMID 30563185, 2018). "We demonstrated for the first time that GAC 17:1 can inhibit activation of STAT3 in U266 cells and also found that GAC 17:1 suppressed IL-6-induced STAT3 activation in multiple myeloma and MEF cells." (PMID 28208828, 2017). "The knockdown of STAT3 and suppression of PI3K each significantly decreased but did not completely abolish Reelin-mediated Cyclin D1 upreguation and myeloma cell proliferation." (PMID 28345605, 2017). "Our findings further reveal that activated Akt and STAT3 pathways induce the upregulation of HIF1α and its downstream targets (LDHA and PDK1), leading to increased glycolysis in myeloma cells." (PMID 28345605, 2017). "Cks1 over-expression leads to multidrug resistance in multiple myeloma cells in vitro by activating MAPK and STAT3 pathways." (PMID 28061788, 2017). "By using AG490, an agent blocking the phosphorylation of AKT and ERK, the proliferation of myeloma cells was inhibited, as well as the phosphorylation of AKT and STAT3, even adding leptin." (PMID 27863383, 2016). "Corresponding to the immunohistochemistry changes, western blot analysis showed icaritin was able to down-regulate significantly the expression of p-JAK2, p-STAT3 and VEGF proteins in myeloma tissue." (PMID 25865044, 2015). "In myeloma cell IL-6 induced proliferation, activation of Src family kinases is required through CD45 molecules as well as activation of STAT3 and MAPK via the IL-6/IL-6 receptor complex." (PMID 26464811, 2015). "Consistently, we confirmed anti-myeloma effect of icaritin in human primary MM xenograft mouse model by down-regulating the levels of p-JAK2, p-STAT3 and VEGF." (PMID 25865044, 2015). "In myeloma cells, IL-6 triggers cell proliferation via at least two intracellular signaling pathways, including JAK/STAT3, and the ras-dependent mitogen-activated protein kinase (MAPK)/extracellular signal-regulated kinase (ERK) cascade." (PMID 25781885, 2015).
multiple myeloma (continued). "Compared to CD45- myeloma cells, CD45+ myeloma cells with an activated JAK/STAT3 pathway are particularly sensitive to JAK2 inhibitor which inhibits IL-6-induced JAK and STAT3 phosphorylation." (PMID 25781885, 2015). "The abrogative effects of small hairpin silencing RNA on targeted STAT3, PI3K and MAPK gene expressions were also observed in 8226 myeloma cells in comparison with control shRNA treatment." (PMID 25422792, 2014). "The findings in this study indicated that RNA silence of STAT3, PI3K, or MAPK gene using shRNA interference robustly inhibited MCL-1 expression in IL-6 treated human MM cells, leading to remarkable myeloma cell apoptosis." (PMID 25422792, 2014). "Our results suggest that berberine suppresses multiple myeloma cell growth, at least in part, by down-regulating miR-21 levels possibly through IL6/STAT3." (PMID 25000828, 2014). "Summary of CK2α, CK2β and STAT3 positivity scores in CD138+ plasma cells of MGUS and Multiple Myeloma cases." (PMID 24086494, 2013). "In this context, signal transducer and activator of transcription 3 (STAT3) phosphorylation that has been shown to be required for memory B cell and ASC formation seems to be impaired by MPA in myeloma cells." (PMID 22571761, 2012). "It has been demonstrated that it acts as a positive regulator of antiapoptotic Stat3/IL-6 receptor signaling by directly suppressing SOCS-1, thereby facilitating malignant growth of multiple myeloma." (PMID 20868483, 2010). "In contrast, 15d-PGJ2 and troglitazone did not affect the expression of IL-6R or activation by phosphorylation of the downstream signaling molecules Jak/Stat3, MAPK, and PI3K/Akt in myeloma cells." (PMID 20204067, 2010). "FLLL32 was also more potent than curcumin to inhibit STAT3 Y705 and JAK2 phosphorylation in U266 and ARH-77 multiple myeloma cell lines." (PMID 20712901, 2010). "Nifuroxazide treatment decreased p-STAT3 in both EV- and CKS1B-transfected myeloma cells compared with untreated controls by western blot, and it did not alter the total protein and phosphorylation of MEK/ERK1 (data not shown), confirming its specificity." (PMID 20930946, 2010). "Incubation of U266-B1 cells with Atiprimod at concentrations ranging from 1 to 8 μM for 1 h significantly downregulated STAT3 phosphorylation, suggesting that Atiprimod inhibits the Janus tyrosine kinase (JAK)-STAT signalling pathway in myeloma cells." (PMID 15970928, 2005). "In 2017, it was again reported to be a promising agent for inhibiting myeloma cell growth, interestingly reducing the phosphorylation of STAT3 but not ERK in response to IL-6 and LIF stimulation." (PMID 40895548, 2025). "In multiple myeloma cells, CHK1 can interact with the STAT3 pathway." (PMID 39314848, 2024). "It was found that a lack of HDAC3 decreases the phosphorylation of STAT3 at Y705 in liver cancer and multiple myeloma." (PMID 37743465, 2023). "Studying MM patients compared with healthy donors and MGUS (monoclonal gammopathy of undetermined significance, early stage of myeloma) subjects, Romano and colleagues showed that CD64 expression on neutrophils increased from healthy to MGUS and to MM patients together with p-STAT3." (PMID 34960234, 2021). "When we added the inhibitor specific for ERK1/2, STAT1, STAT3, or Akt to cocultures of myeloma cells and MSCs, we found that the kinase inhibitor alone or in combination reduced the expression of CXCL1, CXCL2, SDF1, and MCP1 in myeloma cells." (PMID 34150666, 2021). "OncomiR-19a, as a biomarker, may induce better responsiveness to BTZ in myeloma cell lines through itstargets SOCS3, STAT3 and PTEN." (PMID 34837676, 2021). "Additionally, Chong and colleagues demonstrated that IL-6 triggers STAT3 activation and drives the transcription of PRL-3 (an oncogenic phosphatase overexpressed in multiple myeloma)." (PMID 35053027, 2021).